SUCLA2P2 (SUCLA2 pseudogene 2)
Gene: Processed pseudogene on chromosome 2 (76,106,016 to 76,107,324, reverse strand). Ensembl gene ENSG00000233107.
Diseases named in the same sentence as SUCLA2P2 in open-access papers:
SUCLA2P2 is named in the same sentence as 1 disease in open-access papers, as found by Europe PMC text mining. Sharing a sentence is not in itself a finding about the gene and the disease. The quoted sentences say what the papers report.
schizophrenia (1 paper, 2022). A major psychotic disorder characterized by abnormalities in the perception or expression of reality. "Further, SUCLA2P2 has been implicated in the age of smoking initiation and Schizophrenia." (PMID 35285473, 2022).